GAPDH (glyceraldehyde-3-phosphate dehydrogenase)
Diseases named in the same sentence as GAPDH in open-access papers (continued):
Sharing a sentence is not in itself a finding about the gene and the disease.
infection (continued). "The overall prevalence of infection was 100% based on the qPCR result of the housekeeping gene, GAPDH." (PMID 33780500, 2021). "In this study, we demonstrate that the Leishmania GAPDH (LmGAPDH) protein is highly enriched within the extracellular vesicles (EVs) secreted during infection." (PMID 34534548, 2021). "The alum only control mice exhibited 100,000 geomean ZIKV RNA copies per GAPDH copy and succumbed to infection." (PMID 33711018, 2021). "The expression of N protein was completely diminished (normalized to the signal intensity of GAPDH) in cells treated with 15 μM GA on days 3 and 6 post-infection when compared with DMSO-treated cells." (PMID 34681204, 2021). "The main aim of the present study was to develop a rapid quantitative detection test of HPV16 and HPV18 infections by measuring E6 and E7 oncogene DNA levels normalized by the cellular GAPDH gene level." (PMID 33597592, 2021). "Detection of HpHtrA was performed to verify H. pylori strains and CagA and GAPDH served as infection and loading control." (PMID 34742300, 2021). "We also found an increase in surface GAPDH expression of primary neutrophils that were undergoing apoptosis under physiological conditions or after infection with Mycobacterium tuberculosis (H37Rv)." (PMID 34593755, 2021). "Three infection-associated proteins in S. suis—muramidase-released protein (MRP), glyceraldehyde-3-phosphate dehydrogenase (GAPDH), and DLD, a novel putative dihydrolipoamide dehydrogenase—have been previously identified by immunoproteomic assays." (PMID 33671673, 2021). "Under infection conditions β-actin and GAPDH showed similar reductions in transcription when treated with kaempferol, but, markedly, GRP78 was reduced in JEV infection, though the transcriptional level was maintained in DENV infection." (PMID 32164193, 2020). "After 12-h infection, immunoblotting was applied by using α-claudin-8, α-HtrA and α-GAPDH antibodies." (PMID 33364202, 2020). "The expression levels of the three transcripts (I1, I2, I3) in CEF cells infected by RB-1B or CVI-988 at 5 days post-infection (N = 6) were computed and normalised against GAPDH in order to achieve accurate calibration." (PMID 32197378, 2020). "Densitometry quantification confirmed that at the time of infection (24 hpt), Hsp90 protein levels normalized to GAPDH had decreased by ∼60% ± 10%." (PMID 31375577, 2019). "Densitometry quantification confirmed that at the time of infection (24 hpt) the Hsp70 protein levels normalized to GAPDH had decreased by ∼54% ± 8%." (PMID 31375577, 2019). "Previous work from our group showed that DENV infection modulates GAPDH glycolytic activity during the early steps of infection." (PMID 30804377, 2019). "Based on our previous results, GAPDH activity increases in the first 24 h DENV2 post-infection but decreases at 48 h39, which clearly suggests that this enzymatic activity is time-dependent." (PMID 30804377, 2019). "We have previously observed that GAPDH mRNA concentration remains steady in IMR-90 cells infected at a similar MOI for up to 48 hours after infection, therefore GAPDH mRNA was an appropriate reference gene." (PMID 30677073, 2019). "Here, we demonstrated that DENV2 infection redistributes GAPDH from the cytoplasm to the perinuclear region in Huh7.5.1 cells, where the protein localizes with NS3." (PMID 30804377, 2019). "at 24 h post-infection, the cells were lysed, as described in Section 2 and subjected to western blot with anti-HN and anti-GAPDH antibodies (Abs)." (PMID 31096557, 2019). "GAPDH expression levels were similar in infected and uninfected cells, which is in accordance with its unaltered enzymatic activity after infection with HIV-1." (PMID 29518929, 2018). "These peptides led to the identification of a Kupffer cell receptor—CD68—and a Plasmodium sporozoite ligand—GAPDH—that are required for sporozoite traversal of Kupffer cells and subsequent infection of hepatocytes." (PMID 30456380, 2018).
infection (continued). "Neutralizing antibodies were added after 2 h of infection to prevent secondary infection cycles and the intensity of the bands was quantified relative to cellular GAPDH, used as a loading control." (PMID 29584637, 2018). "It is significant that GAPDH from many different bacteria is exported to the bacterial cell wall and the extracellular space, where it seems to acquire functions that facilitate infection through direct binding to innate immune proteins." (PMID 28443070, 2017). "The expression levels of Egr-1 and respective GAPDH at different time points (2, 6, 12 and 24h) post-infection are shown in THP-1 and HUVECs transfected with either pA3F-Egr-1 or pA3F (empty vector) (c for THP-1 and 7B, c for HUVECs)." (PMID 29207655, 2017). "Data are presented as the mean (±standard deviation) of triplicate PCR measurements per 106 copies feline GAPDH cDNA, and are representative of PBMCs at 258–262 weeks post-infection for each cat." (PMID 29056720, 2016). "Studies using recombinant B. abortus derived GAPDH induced both humoral and cellular immune responses during experimental infection with B. abortus in natural hosts (cattle and sheep) and mice." (PMID 27144565, 2016). "Early in light infection, host genes for the key Calvin cycle enzymes glyceraldehyde-3-phosphate dehydrogenase (gap2) and phosphoribulokinase (prkB) are diminished while the host gene for CP12 (cp12) is enriched." (PMID 27788196, 2016). "It appears that during infection, more GAPDH is secreted into the extracellular milieu to capture Lf (and the Lf bound iron) for rapid sequestration into surrounding host cells." (PMID 26672975, 2015). "Total glycolytic GAPDH enzymatic activity increased during infection with virulent or avirulent Pst DC3000 as well as after perception of flg22." (PMID 25918875, 2015). "We developed a vaccine targeting the GBS glyceraldehyde-3-phosphate dehydrogenase (GAPDH), a glycolytic enzyme detected at the bacterial surface, which was proven to be effective in a neonatal mouse model of infection." (PMID 26673420, 2015). "After successfully identifying homozygous GAPDH KO lines, we subjected them to a variety of disease assays to determine their relative contribution during infection with Pseudomonas syringae pv." (PMID 25918875, 2015). "GAPDH mRNA was also identified in the P. brasiliensis transcriptome from mouse liver, which reinforces its potential role in the infection process." (PMID 25566229, 2014). "The avian viruses as well as the H3N2 virus were cytopathic for human cells as evidenced by a detectable decrease in GAPDH protein levels at 24 h after infection." (PMID 24804732, 2014). "P. aeruginosa infection induced IL-8 mRNA and hBD-2 mRNA expression (normalized to GAPDH) after one-hour infection in SW480 cells." (PMID 25433669, 2014). "We compared the surface expression patterns of BMDMs or DCs loaded with purified LLO or GAPDH, or after infection with LM-WT." (PMID 24600592, 2014). "Different stimulation and infection experiments were successfully conducted for further confirmation of stable β-Actin and GAPDH expressions despite this was already shown by preliminary studies." (PMID 25268123, 2014). "The loss of tetherin expression was somewhat specific, as β-actin and transferrin receptor protein levels were unaffected up to 16 h after infection and GAPDH levels were only slightly reduced." (PMID 24067975, 2013). "In Macrosteles quadripunctulatus, BestKeeper and Normfinder analysis indicated ATP synthase β, tropomyosin and GAPDH as the most stable, whereas geNorm identified reliable genes only for early stages of infection." (PMID 24119747, 2013). "Pre-mRNAs transcribed from the IL6, IFIT2 and STAT1 genes were present in mock-infected cells, and decreased significantly in concentration following infection with AdEasyE1, whereas only minimal differences in GAPDH mRNA were detected." (PMID 22912576, 2012).
infection (continued). "The amount of mRNA specific for the housekeeping gene GAPDH was related to the amount of MHC I mRNA at different times after infection." (PMID 22809544, 2012). "Altogether, these results strongly suggest that the elevated IL-10 serum levels detected upon infection were due to GBS GAPDH." (PMID 22114550, 2011). "We identified extracellular GAPDH as the GBS factor that induces the high IL-10 production detected early upon neonatal infection." (PMID 22114550, 2011). "We show that maternal vaccination with recombinant GAPDH confers robust protective immunity against lethal infection with a GBS hyper-virulent strain in mice offspring." (PMID 22114550, 2011). "An upregulation of the transcription of amphiregulin mRNA was detected after infection compared to untreated cells and normalized to housekeeping gene GAPDH." (PMID 21298020, 2011). "GAPDH contributes to the adhesion of Paracoccidioides brasiliensis to host tissues and to the dissemination of infection." (PMID 20144196, 2010). "The increased gluconeogenesis during LCMV infection resembled that seen during starvation or cachexia, however the infection also up-regulated mRNA encoding glycolytic enzymes (PGK1, GCK, GAPDH and ALDOB) that are usually down-regulated during a fast." (PMID 19216742, 2009). "The degree of variation of GAPDH mRNA from sample to sample was within 5% of the mean expression level in both infected and uninfec ted control samples throughout the course of the infection." (PMID 16359553, 2005). "While our initial analysis highlighted GAPDH as a highly stable reference gene, particularly during the 18th and the 23rd days after infection, it is important to note that the geNorm analysis recommends using multiple reference genes for more robust normalization when V4/5 < 0.15." (PMID 41156676, 2025). "However, in pathogen infection assays, both F. oxysporum and F. solani infections significantly increased GAPDH enzyme activity." (PMID 40573855, 2025). "Furthermore, we compared the number of BeWo cells in infection experiments using different T. cruzi strains by means of a qPCR test targeting the human GAPDH gene." (PMID 39165920, 2024). "In addition, the effect of E. tenella activity on the endogenous developmental stage was evaluated by measuring gene expression of E. tenella GAPDH, at different infection time points." (PMID 38243250, 2024). "The Leishmania major GAPDH protein is highly enriched within the EVs secreted during infection." (PMID 37046327, 2023). "Additionally, GAPDH showed the best stability in Pythium porphyrae under conditions of salinity, pH and infection stages." (PMID 37894879, 2023). "Observation of the interaction between gRNA and GAPDH could additionally facilitate the shuttling of GAPDH into the nucleus at the early stages of infection where it would later increase the rate of cis-cleavage during the rolling circle replication." (PMID 37632029, 2023). "Because of the involvement of NETs in a variety of diseases, our results raise the question of whether control of NET formation by GAPDH plays a general role in inflammation or infection." (PMID 37147288, 2023). "There is a relationship between glutamate and GAPDH shown previously, so, it can be inferred that the differential levels observed in controllers can promote the downregulation of the infection." (PMID 37457832, 2023). "The control GAPDH gene was stably expressed at the site of infection in all groups." (PMID 36894548, 2023). "In addition, recent studies have shown that the Leishmania GAPDH (LmGAPDH) protein is highly enriched in EVs secreted during infection, and GAPDH can inhibit the expression of TNF-α in a host." (PMID 36035188, 2022). "With GAPDH normalization, even asymptomatic patients exhibited significant induction of IL-6, and the IL-6 expression was also comparable with that of patients having moderate infections and those with CAM." (PMID 36377893, 2022).
infection (continued). "Speculatively, in the process of infection, M. hyorhinis first uses adhesion factors such as GAPDH to bind the ECM, facilitating adhesion and colonization." (PMID 34082810, 2021). "The presence of Leishmania-kDNA in respect to Mφ-GAPDH determined the degree of infection, in vivo." (PMID 33732662, 2021). "Maternal vaccination with GBS GAPDH protects newborns against infection." (PMID 30224677, 2018). "Since S. pyogenes, A. vaginae, and S. typhimurium are all important human pathogens, the immunoevasive capacity detected for bacterial GAPDH might conceivably have been selected for in the context of infection." (PMID 28443070, 2017). "Unfortunately, none of the tested mutant strains except for the strain with a targeted gene for glyceraldehyde-3-phosphate dehydrogenase (GapA, FTS_1117) revealed any signs of attenuation, as, similarly to the wt strain, all the challenged mice succumbed to infection around the 5th day." (PMID 29322032, 2017). "The anaerobic lifestyle of A. vaginae implies that a functional glycolytic pathway might be important to sustain infection, therefore making A. vaginae (Av) GAPDH an interesting target for the design of potent inhibitors." (PMID 28443070, 2017). "Moreover, infection with rBDV-miR-GAPDH seemed to reduce the expression of GAPDH in the somas of the neurons (arrows)." (PMID 27189575, 2016). "A recent study has also investigated the use of the normalization control genes ACT, TUBA and GAPDH, together with small nucleolar RNAs and microRNAs, under a range of stress treatments, including infection with the necrotrophic fungal pathogen Rhynchosporium commune." (PMID 26238194, 2016). "To determine whether individual Arabidopsis GAPDH isoforms play a role during infection with Pst DC3000, we screened T-DNA insertion lines for knockout (KO) lines in distinct isoforms." (PMID 25918875, 2015). "Interestingly, levels of 12S mRNA were approximately 3-fold higher than 13S mRNA (5.2% vs. 1.5% of GAPDH levels) while levels of other E1A transcripts were negligible at 24 hours after infection." (PMID 26448631, 2015). "Therefore, we do not recommend the further employment of these genes as normalization controls in qRT-PCR analysis of tomato genes after pathogen infection, especially because we clearly showed an Xcv-dependent downregulation of GAPDH expression." (PMID 26313760, 2015). "Both GAPDH and RPL30 possess a pattern of histone modifications typical of permissive chromatin, similar to those associated with most CMV viral loci during late times of infection." (PMID 25166009, 2014). "However, Ct values of the other genes spanned a greater range over the course of infection; tubulin (16.27–22.9), beta actin (26.6–30.8), GAPDH (22.4–28.9), and L35 (15.0–22.1)." (PMID 25313905, 2014). "Additionally, increased HCV NS3 and NS5A protein expression were observed via Western blot in Huh7.5JFH1 cells infected with HIVNL4-3 at days 1, 3, 7, and 14 post-infection compared to uninfected control levels after normalization to GAPDH protein levels." (PMID 24586227, 2014). "The researchers showed that GAPDH was overexpressed during infection, and similar results were observed when P. brasiliensis yeast cells were incubated with human blood, which supports the notion that this molecule may be involved in pathogenesis." (PMID 25566229, 2014). "GAPDH, which is usually used as a loading control in Western blots, was seen at a 1∶1 infected to mock ratio in all three experiments at both the 6 and 24 hour infection time points, and had SILAC ratios of 1.09±0.11." (PMID 23240068, 2012). "Thus, neutralization of GAPDH, and hence blockade of the induced IL-10 production, allowed an effective immune response at an early stage of infection that prevented death of pups." (PMID 22114550, 2011). "GAPDH and the small GTPase Rab 2 are involved in Brucella replication at late post-infection." (PMID 19557163, 2009).
infection (continued). "Interestingly, the amount of nuclear-GAPDH decreased in early infection, increased between 12 to 24 h postinfection, and decreased again at 36 h postinfection." (PMID 19368702, 2009). "This study highlights the findings that infection of JEV changes subcellular localization of GAPDH suggesting that this metabolic enzyme may play a role in JEV replication." (PMID 19368702, 2009). "Hence, we speculate that inhibition of GAPDH might help in the treatment of infection with viruses such as SARS‐CoV‐2." (PMID 33185982, 2021). "Firstly, because GAPDH is an essential gene present in all bacteria and could therefore be seen as a universal virulence factor tasked with down-regulating complement-mediated recruitment of neutrophils to sites of infection." (PMID 28443070, 2017). "This molecule seems to play a role in the initial steps of infection once in vitro assays demonstrated the inhibition of adhesion and infection of P. lutzii to pneumocytes after fungus incubation with anti-GAPDH antibody or cell treatment with recombinant GAPDH." (PMID 26635779, 2015). "The results showed that metformin treatment increase mRNA expression of GAPDH over mock infection, and surprisingly DENV 2/metformin increased GAPDH over infection alone." (PMID 38594438, 2024). "After 48 hours of infection, circHMGCS1 and HMGCS1 expression levels were assessed by qRT-PCR and normalized to GAPDH (n=4)." (PMID 39235443, 2024). "The RT-qPCR data were normalized to the mean value of the transcriptionalactivity of two housekeeping genes (GAPDH andSDHA) since their expression profile was only marginallyaffected (SDHA; log2 = 0.2, P = 0.3; GAPDH;log2 = 0.2, P = 0.04) upon AAV2 infection." (PMID 38837381, 2024). "After infection for 72 h, the cells were harvested, and the proteins of Hrd1, CDV N, and GAPDH were tested by Western blot." (PMID 37009870, 2023). "We performed RT-qRT-PCR for S1PR1 messenger RNA (mRNA) relative to the housekeeping gene GAPDH on total mock and HIV-infected thymocytes at weeks 5 and 9 post-infection (schematics)." (PMID 37762169, 2023). "RT-qPCR measurements were taken late during infection at 48 h and 72 h post reactivation of viral RNA from the K8.1 (late) and ORF66, ORF6, and ORF68 (early) loci, as well as cellular GAPDH." (PMID 37068108, 2023). "The cells were collected 24 h post-infection, lysed, and subjected to SDS-PAGE/western blot analysis using antibodies against matriptase, prostasin, or GAPDH, respectively." (PMID 37568664, 2023). "We therefore repeated the post-infection treatment experiment and determined the level of expression of four DENV proteins (E, NS1, NS3 and NS5) as well as the expression of GAPDH for normalization by western blotting." (PMID 35509105, 2022). "While total TrkA and GAPDH remained similar, strong pTrkA was detected as early as 15 min post-infection, demonstrating that IAV infection activates TrkA early in the infection." (PMID 36121891, 2022). "We observed a substantial reduction (greater than 10-fold) in GAPDH and ACTB mRNAs in SARS-CoV-2-infected cells WTACE2 cells as early as 8 h post-infection." (PMID 34315815, 2021). "After infection with TBSV, GAPDH moves from the cytoplasm to the peroxisomal membrane and into the sites of TBSV replication." (PMID 33920930, 2021). "Using qRT-PCR, these researchers showed that this reduction was vhs dependent based on two sets of genes that exhibited either high (COL6A2, MMP3, and MMP1) or low (GAPDH, ACTB, and RPLP0) reduction in total RNA levels in WT infection." (PMID 33148793, 2021). "Total RNA of BMDMs infected with ASFV SY18 or mock infection were detected by the late viral gene B646L (p72), the early viral gene CP204L (p30), I267L and GAPDH (housekeeping gene)." (PMID 35062257, 2021). "The cultures were harvested at indicated time points after infection, followed by solubilization, electrophoresis in denaturing gels, and incubation with antibodies against ICP27, ICP8, VP16, US11, GFP, and GAPDH." (PMID 32390978, 2020).